RSPH10B (radial spoke head 10 homolog B)
Description:
May function as part of the axonemal radial spoke complex 3 (RS3). Radial spoke complexes are important for ciliary motility.
Tractability: Antibody: the Human Protein Atlas places it where antibodies can reach.
Gene: Protein-coding gene on chromosome 7 (5,925,550 to 5,970,702, reverse strand). Ensembl gene ENSG00000155026.
Subcellular location: Cytoplasm, cytoskeleton, cilium axoneme; Cell projection, cilium; Cell projection, cilium, flagellum
Subcellular location (Human Protein Atlas): Primary cilium; Cytosol; Microtubules; Plasma membrane
Gene Ontology:
Cellular component: cilium; sperm flagellum; 9+2 motile cilium; axoneme; motile cilium
Genetic constraint (gnomAD): Loss-of-function variants: 3 observed, 17.12 expected, observed/expected ratio (o/e) 0.18, 90% interval 0.079 to 0.45. The synonymous counts are far from expectation, so gnomAD's model fits this gene poorly and the ratio says little. Missense variants: 56 observed, 172.21 expected, observed/expected ratio (o/e) 0.33, 90% interval 0.26 to 0.41. Synonymous variants: 21 observed, 50.49 expected, observed/expected ratio (o/e) 0.42, 90% interval 0.29 to 0.6.
Homologues: Orthologues: mouse Rsph10b (73% identical), rat Rsph10b (73% identical), tropical clawed frog rsph10b (44% identical). Paralogues in human: RSPH10B2 (99% identical), ALS2CL (15% identical), MORN1 (11% identical), RSPH1 (9% identical), MORN3 (9% identical), SETD7 (7% identical), MORN2 (4% identical).
Diseases named in the same sentence as RSPH10B in open-access papers:
RSPH10B is named in the same sentence as 1 disease in open-access papers, as found by Europe PMC text mining. Sharing a sentence is not in itself a finding about the gene and the disease. The quoted sentences say what the papers report.
Kartagener Syndrome (1 paper, 2021). An autosomal recessive disorder characterized by a triad of DEXTROCARDIA; INFERTILITY; and SINUSITIS. "RSPH10B, the most statistically significant TWAS gene, was reported to play a crucial role in ciliary and flagellar axonemes and to be associated with Kartagener syndrome." (PMID 33809961, 2021). "Based on this information, we believe that RSPH10B may actually affect the pathogenesis of ALS and have a shared genetic contribution to Kartagener syndrome." (PMID 33809961, 2021).